CRH (corticotropin releasing hormone)
Diseases named in the same sentence as CRH in open-access papers (continued):
Sharing a sentence is not in itself a finding about the gene and the disease.
fibromyalgia (5 papers, 2005 to 2025). A chronic disorder of unknown etiology characterized by pain, stiffness, and tenderness in the muscles of neck, shoulders, back, hips, arms, and legs. "The stress-induced activation of the hypothalamic–pituitary–adrenal (HPA) axis is triggered by the release of a corticotropin-releasing hormone that has been previously reported in the pathogenesis of fibromyalgia." (PMID 40430245, 2025). "In patients with fibromyalgia, the levels of corticotropin-releasing hormone (CRH), were increased in the serum and cerebrospinal fluid and correlated with the severity of pain." (PMID 32054062, 2020). "Dysregulation of the circadian variation in cortisol and response to corticotropin-releasing hormone has been observed in fibromyalgia, alongside potential correlation with symptom severity, further implicating the HPA axis, although data in this area are inconclusive." (PMID 40002538, 2025). "Thus, Crofford and colleagues reported that fibromyalgia clinic patients had low 24-h urinary free cortisol levels and low levels of cortisol in response to challenge with ovine corticotropin-releasing hormone when compared to age- and sex-matched pain free controls." (PMID 16207340, 2005). "Similar tests performed with fibromyalgia patients found an exaggerated ACTH response, but blunted cortisol response to CRH injection." (PMID 34026797, 2021). "Substance P is the neuropeptide most consistently demonstrated to be elevated fibromyalgia, although other neuropeptides such as MCP-1, brain-derived neurotrophic factor, corticotrophin-releasing hormone (CRH), hemokinin-1 (HK-1), and calcitonin gene-related peptide are also implicated." (PMID 40002538, 2025). "Researchers have injected fibromyalgia patients simultaneously with CRH, TRH, GHRH as well as GnRH—however, this was not done in order to assess the therapeutic potential of secretagogues but to study the patients' endocrine dysfunctions." (PMID 34026797, 2021).
hypocortisolemia (5 papers, 2021 to 2024). "Most patients in the unexplainable-HD group had undergone the CRH challenge test to examine hypocortisolemia, detected during the screening for chronic fatigue." (PMID 36494805, 2022). "For example, dysregulation of the HPA axis can be confirmed by hypocortisolemia (low levels of cortisol) in blood plasma against a background of increased corticotropin-releasing hormone (CRH) in cerebrospinal fluid." (PMID 36703926, 2022).
hypothyroidism (5 papers, 2014 to 2025). Abnormally low levels of thyroid hormone. "A significant decrease in the expression of CRH mRNA in the paraventricular nucleus (PVN) of the hypothalamus in rats with hypothyroidism was revealed." (PMID 34104248, 2021). "According to their study, short-term hypothyroidism was associated with increased pituitary corticotroph responsiveness to corticotropin-releasing hormone in contrast with long-term hypothyroidism." (PMID 27611926, 2016).
neuroblastoma (5 papers, 2011 to 2025). Neuroblastoma (NB) is the most common solid, extracranial childhood tumor. "Activation of CRHR1 by CRH has been shown to increase the release of APP in rat cerebellar neurons, in human neuroblastoma IMR32 cell line, and in mouse hippocampal HT22 cells." (PMID 38706793, 2024).
paraganglioma (5 papers, 2013 to 2026). A benign or malignant neoplasm arising from paraganglia located along the sympathetic or parasympathetic nerves. "Similar to common paragangliomas, the composite paragangliomas are primarily functional, secreting catecholamines such as adrenaline, noradrenaline, and dopamine or corticotrophin-releasing hormone (CRH) as well." (PMID 35273997, 2022).
postnatal depression (5 papers, 2015 to 2024). "Researchers have gone so far as to say that elevated CRH levels may be used as a diagnostic criterion for postpartum depression." (PMID 26819762, 2016). "Altered levels of cortisol, ACTH, and CRH have been associated with postpartum depression." (PMID 26819762, 2016). "Accordingly, it has been suggested that CRH levels are increased in women with postpartum depression and may even be used as a diagnostic criteria for postpartum depression." (PMID 26819762, 2016). "It is known that HPA axis regulation is influenced by cortisol, ACTH, and CRH, but in women with postpartum depression, studies have identified a hyperactive HPA axis." (PMID 39598226, 2024). "We used the keywords “HPA axis hormone” OR “CRH” OR “ACTH” OR “cortisol” AND “postpartum depression” OR “postnatal depression” OR “maternal depression”." (PMID 35903273, 2022). "Most studies involve CRH measurement assessed the secretion during pregnancy (testing pCRH), and immediate after delivery to predict the onset of postpartum depression." (PMID 35903273, 2022). "More convincing evidence exists for increased levels of CRH and ACTH associated with postpartum depression." (PMID 26819762, 2016). "CRH, ACTH and cortisol evaluation in the postpartum depression studies." (PMID 35903273, 2022). "One study has found that corticotropin-releasing hormone levels (CRH) in mid-pregnancy are associated with prenatal, but not postnatal depression but overall the literature on maternal mental health and CRH in pregnancy shows mixed findings." (PMID 27417821, 2015).
sleep disorder (5 papers, 2013 to 2024). A change from the patient's baseline sleeping pattern, in the hours slept and/or an alteration/dysfunction in the stages of sleep. "In this article we report a novel mutation (p.Pro30Arg) within the CRH gene cosegregating with sleep disorders (i.e. ADNFLE and RBD) and detected in an Italian family." (PMID 23593457, 2013). "In addition, prolonged central CRH secretion is thought to be associated with sleep disorders." (PMID 36713913, 2022). "Increased CRH levels/activity has been found in both rodent models of sleep disorders and in patients with sleep problems." (PMID 36611953, 2022).
Stroke (5 papers, 2022 to 2025). Sudden impairment of blood flow to a part of the brain due to occlusion or rupture of an artery to the brain. "Following a stroke, the hippocampus and adjacent brain regions send signals to the hypothalamus, stimulating the release of corticotropin-releasing hormone (CRH)." (PMID 40529498, 2025). "That said, stress—a common pathological condition among stroke patients—can increase intestinal permeability through mast cell activation mediated by corticotropin-releasing hormone (CRH)." (PMID 39767686, 2024). "In the current study, we found the overall increased hypothalamic CRH, pituitary POMC, and plasma corticosterone levels in both normal and diabetic mice after stroke." (PMID 35784349, 2022). "We also confirmed increased levels of hypothalamic CRH, pituitary POMC, and plasma corticosterone in diabetic mice before and after stroke, suggesting the hyper-activated HPA axis in diabetic conditions." (PMID 35784349, 2022). "The stress response during the acute stroke phase overactivates the HPA axis, triggering the hypothalamus to secrete corticotropin-releasing hormone (CRH) and the pituitary gland to release adrenocorticotropic hormone (ACTH), ultimately leading to excessive cortisol secretion by the adrenal cortex." (PMID 41403899, 2025). "Gene expression of hypothalamic CRH was similar in ND/veh and DD/STZ mice prior to stroke." (PMID 35784349, 2022).
adrenal tumor (4 papers, 2019 to 2023). "Next, we analyzed the DEGs between ACTH+&CRH + pheochromocyte and the other two subtypes of adrenal tumor cells (pheochromocyte and adrenocortical cells)." (PMID 34905486, 2021). "Differential diagnosis must include primary adrenal tumors, ectopic ACTH or Corticotropin-releasing Hormone (CRH) production and it is based on specific pediatric endocrine work-up that includes cortisol-suppression and ACTH and cortisol stimulation tests." (PMID 35455578, 2022).
androgen excess (4 papers, 2009 to 2025). "Adrenal androgen excess in women with PCOS may not be related to an altered pituitary response to CRH or to increased sensitivity to ACTH." (PMID 19680559, 2009).
anorexia nervosa (4 papers, 2004 to 2024). A disorder most often seen in adolescent females characterized by a refusal to maintain a minimally normal body weight, an intense fear of gaining weight, a disturbance in body image, and, in postmenarcheal females, the development of amenorrhea. "Stress induced (hypothalamic) amenorrhea, as well as exercise-induced amenorrhea and anorexia nervosa, activate the HPA axis, increasing cortisol secretion and decreasing corticotropin or cortisol response to exogenous CRH." (PMID 15588275, 2004).
COVID-19 (4 papers, 2020 to 2023). A disease caused by infection with severe acute respiratory syndrome coronavirus 2. "Microglia express receptors for neurotensin (NT) and corticotropin-releasing hormone (CRH), secreted under stress, which are especially associated with COVID-19." (PMID 36899824, 2023). "WikiPathways enrichment analysis showed that XBJ acted on COVID-19 mainly through 40 pathways, such as HIF-1 survival, TWEAK, corticotropin-releasing hormone, RANKL/RANK, B Cell Receptor Signaling Pathway, and Ras Signaling Pathway." (PMID 33082858, 2020).
Hyperinsulinemia (4 papers, 2014 to 2022). An increased concentration of insulin in the blood. "Hyperinsulinemia increased CRH, ACTH and corticosterone in rats and a similar increase in ACTH and cortisol was observed in healthy, lean men in response to acute supraphysiologic insulin infusion." (PMID 35544473, 2022).
hypopituitarism (4 papers, 2020 to 2024). A condition of diminution or cessation of secretion of one or more hormones from the anterior pituitary gland. "In our case, the decreased ACTH level and the low response to the CRH stimulation test indicated that the AI was due to hypopituitarism." (PMID 38910605, 2024). "Hypopituitarism is present when CRH-stimulated plasma ACTH levels are less than 10pg/ml." (PMID 36743928, 2022). "K) Seven days after hypophysectomy, CRH loading test is performed to confirm hypopituitarism." (PMID 36743928, 2022). "Eight patients had false-negative test results with the CRH test (normal test but adrenal insufficient at follow-up), and six patients with basal cortisol, the majority of which had multiple pituitary hormone deficiencies and fluid imbalances." (PMID 31556005, 2020).
osteoporosis (4 papers, 2017 to 2024). A condition of reduced bone mass, with decreased cortical thickness and a decrease in the number and size of the trabeculae of cancellous bone (but normal chemical composition), resulting in increased fracture incidence. "Previous research demonstrated that acupuncture at ST36, BL23, and BL11 acupoints regulated serum levels of estradiol, corticotropin-releasing hormone, adrenocorticotropin, and corticosterone, thereby improving osteoporosis." (PMID 39588119, 2024). "Herein, we characterize the molecular and physiologic effects of GC‐induced osteoporosis using the Cushing's mouse model, the corticotropin releasing hormone (CRH) transgenic mouse (CRH‐Tg)." (PMID 30283880, 2017).
ovarian carcinoma (4 papers, 2007 to 2024). A malignant neoplasm originating from the surface ovarian epithelium. "Our study indicates that intratumoral expression of CRH and FasL is associated with advanced tumour stage in ovarian cancer." (PMID 17667919, 2007). "CRH expression is associated with the advanced stage of ovarian cancer." (PMID 35464849, 2022). "Using both ovarian cancer tissue and two ovarian cancer cell lines, Minas and colleagues demonstrated that CRH contributes to the immune privileges of ovarian tumors." (PMID 36552294, 2022). "Regarding the molecular mechanism, the authors provided evidence that CRH acts on ovarian cancer through CRHR1, which upregulates the expression of Fas ligands (FasL), potentiating the ability to induce Fas-mediated apoptosis." (PMID 36552294, 2022). "Although corticotropin-releasing hormone (CRH) and Fas ligand (FasL) have been documented in ovarian carcinoma, a clear association with tumour progression and immuno-escape has not been established." (PMID 17667919, 2007). "In all cases, apoptosis was significantly lower than in co-cultures with CRH-treated ovarian cancer cells (P<0.05)." (PMID 17667919, 2007). "We found that CRH upregulates the expression of FasL in two human ovarian cancer cell lines (OvCa3 and A2780), thereby potentiating their ability to induce Fas-mediated apoptosis of activated PBL." (PMID 17667919, 2007). "We suggest that apoptosis of PBL was mainly owed to Fas–FasL interaction for the following reasons: Addition of an anti-Fas blocking antibody reverted the effect of CRH-treated ovarian cancer cells, by significantly reducing the numbers of apoptotic PBL." (PMID 17667919, 2007). "The present study confirms the expression of CRH and reports for the first time the expression of CRH receptors in ovarian cancer in situ." (PMID 17667919, 2007). "Moreover, the authors found that incubation of ovarian carcinoma cells with CRH resulted in FASL upregulation, through activation of CRHR1 receptors, ultimately inducing increased apoptosis of activated T lymphocytes." (PMID 37382757, 2024). "Indeed, CRH acted on the ovarian cancer cells OvCa3 and A2780, through CRHR1, to upregulate the expression of FasL and thus potentiate the ability of the cells to induce Fas-mediated apoptosis of activated PBL." (PMID 17667919, 2007). "Corticotropin-releasing hormone produced by human ovarian cancer might favour survival and progression of the tumour by promoting its immune privilege." (PMID 17667919, 2007). "Peripheral corticotropin-releasing hormone (CRH) has been detected in ovarian carcinoma." (PMID 17667919, 2007). "The results of the present study suggest that tumour-produced CRH might be an autocrine–paracrine factor, which together with others, modulates the expression of FasL in ovarian cancer." (PMID 17667919, 2007). "The ovarian cancer cell lines OvCa3 and A2780 were further used to test the hypothesis that CRH might contribute to the immune privilege of ovarian tumours, by modulating FasL expression on the cancer cells." (PMID 17667919, 2007). "Addition of 2 μg of the antibody, blocked the effect of CRH-treated ovarian cancer cells on PBL apoptosis (6±2% apoptotic PBL in TUNEL and 7±3% in poly-caspase assay for co-cultures with OvCa3, 7±1% in TUNEL and 7±3% in poly-caspase for co-cultures with A2780)." (PMID 17667919, 2007). "Here, we examined immunohistochemically the expression of CRH, CRHR1, CRHR2 and FasL in 47 human ovarian cancer cases." (PMID 17667919, 2007). "In the present study, we examined the distribution of CRH, CRHR1, CRHR2 and FasL peptides in ovarian carcinoma and we investigated the potential role of CRH and FasL in modulating the immune defenses of ovarian cancer cells." (PMID 17667919, 2007). "Furthermore, CRH alone induced low levels of PBL apoptosis, comparable to those measured in co-cultures with ovarian cancer cells without any additives." (PMID 17667919, 2007).
substance abuse (4 papers, 2016 to 2025). The use of a drug for a reason other than which it was intended or in a manner or in quantities other than directed. "Hippocampal CRH secretion is known to contribute to stress-induced substance abuse and increased activation of pyramidal target neurons via CRHR1, which tend to produce anxiogenic effects." (PMID 29379100, 2018). "The HPA axis, and extrahypothalamic CRH, are thought to be involved in adult responses to both acute and chronic ethanol exposure, and show characteristic responses to ethanol and other substance abuse in humans and in mammalian models, and also in zebrafish." (PMID 26862749, 2016).
substance dependence (4 papers, 2012 to 2021). The psychological or physiological need to take a substance in order to experience its effects or to avoid the effects of its absence. "The CRF (also known as corticotropin-releasing hormone, CRH) system coordinates not only neuroendocrine and autonomic responses to stressors, but also to substance dependence." (PMID 27385383, 2016). "Accordingly, we have observed that the increase in the number of CRH neurons in the BNST and CeA during morphine dependence was abolished after adrenalectomy." (PMID 23185589, 2012).
vitiligo (4 papers, 2020 to 2025). Generalized well circumscribed patches of leukoderma that are generally distributed over symmetric body locations and is due to autoimmune destruction of melanocytes. "Our finding revealed that T-allele and TT-genotype were significantly associated with vitiligo, and the level of CRH was significantly higher in cases with TT-genotype subgroup." (PMID 35905107, 2022). "This study was aimed at investigation of the serum levels of BDNF and CRH as well as their selected single nucleotide polymorphisms (SNPs) in vitiligo patients in comparison with the healthy controls." (PMID 35905107, 2022). "The authors found a substantial rise in expression of CRH and CRH-R1 in both damaged and undamaged skin of patients with vitiligo and observed a significant direct association with stress levels." (PMID 35905107, 2022). "The aim of our study was to investigate the serum levels of BDNF and CRH, as well as their individual SNPs, in patients with vitiligo and healthy comparators." (PMID 35905107, 2022). "Our recent study also demonstrated the decreased level of serum BDNF and increased level of serum CRH in vitiligo patients in comparison with the healthy controls." (PMID 35905107, 2022). "The serum levels of BDNF were significantly lower in vitiligo patients than in healthy individuals, while the serum levels of CRH were markedly higher in cases than those in controls." (PMID 35508633, 2022). "The serum levels of BDNF were significantly lower in vitiligo patients than in healthy individuals (Z = 4.002; P < 0.001), while the serum levels of CRH were markedly higher in cases than those in controls (Z = 3.764; P < 0.001)." (PMID 35508633, 2022). "Median serum CRH level was 6.39 (2.46–8.31) in vitiligo patients and 3.24 (2.18–3.85) in healthy subjects (P < 0.001)." (PMID 35508633, 2022). "Only serum CRH level had poor prognostic value for forecasting of vitiligo event, which was statistically significant (AUC = 0.657) with cut-off point 0.222 at sensitivity equal to 0.938 and specificity equal to 0.990." (PMID 35508633, 2022). "However, in our study serum CRH level was significantly higher in vitiligo patients as compared with controls." (PMID 35508633, 2022). "The genes encrypting brain-derived neurotrophic factor (BDNF) and corticotropin releasing hormone (CRH) might be the conceivable contributors to the development of vitiligo." (PMID 35905107, 2022). "Thus, we aimed to investigate the serum levels of BDNF and CRH as well as their selected SNPs in vitiligo patients and healthy controls." (PMID 35905107, 2022). "Besides, the in vitro studies and clinical evidence of direct and indirect pro-inflammatory action of CRH were reported for vitiligo." (PMID 35508633, 2022). "In the literature, there is only one report describing the role of CRH and CRH-R1 in vitiligo." (PMID 35905107, 2022). "In fact, psychiatric biomarkers such as brain-derived neurotrophic factor (BDNF) and corticotropin-releasing hormone (CRH) have been found to be down and upregulated respectively in vitiligo patients." (PMID 40303919, 2025). "To date, there are practically no studies devoted to determine the serum levels of CRH in vitiligo patients." (PMID 35508633, 2022).